PFN1 (profilin 1)
Diseases named in the same sentence as PFN1 in open-access papers (continued):
Sharing a sentence is not in itself a finding about the gene and the disease.
infection (6 papers, 2011 to 2023). The state of being infected such as from the introduction of a foreign agent such as serum, vaccine, antigenic substance or organism. "Cells with Pfn1 overexpression and downregulation were established separately using a lentiviral infection system." (PMID 25103363, 2014). "With the exception of profilin 1, these actin binding proteins were significantly decreased in animals with active infection." (PMID 21507248, 2011). "Specifically, the concentration of profilin 1, α actinin, vinculin, and filamin A were found to be significantly altered by infection." (PMID 21507248, 2011). "Interestingly, our network analysis also identified a potential new role for miRNA-342 in cytoskeleton regulation (PFN1, PXN) during infection." (PMID 30619110, 2018). "In lung macrophages, PFN1 (ENSG00000108518) is a key actin regulatory protein that is involved in the regulation of actin filament assembly, which may be related to the migration of macrophages to the site of infection." (PMID 37007947, 2023).
neurological diseases (2 papers, 2021 to 2022). "Particularly, studies on neurological diseases emphasize both the biomedical relevance and the functional diversity of PFN1 and PFN2a isoforms." (PMID 34458253, 2021).
bacterial infections (1 paper, 2025). "Whereas Class2 uniquely included pathways related to bacterial infections (e.g., E. coli, Salmonella) together with actin-cytoskeleton and T-cell modules (e.g., ACTB, PFN1, RAC2, PIK3CD, CD3D/CD3G, STING1, TRADD, CASP8, BCL2, HLA-F)." (PMID 41394852, 2025).
genetic disorder (1 paper, 2024). "Heterozygous deletions of the PFN1 gene have also been observed in patients with a severe phenotype of Miller–Dieker syndrome, a rare genetic disorder caused by a contiguous gene deletion." (PMID 39769211, 2024).
PFN1 also shares sentences with these, for which no sentence is quoted: adenocarcinoma (5 papers); cardiovascular diseases (4); acute myocardial infarction (3); spinal muscular atrophy (3); chronic kidney disease (2); non-small cell lung carcinoma (2); adenoma (1); adenovirus infection (1); adrenoleukodystrophy (1); Alzheimer disease (1); aortic atherosclerosis (1); brain glioma (1); cervical cancer (1); clear cell carcinoma (1); clear cell renal cell carcinoma (1); cognitive decline (1); depression (1); diabetic retinopathy (1); endometrioid carcinoma (1); fungal keratitis (1); gastrointestinal tract cancer (1); giant cell tumour of bone (1); glomerulonephritis (1); heart (1); heart failure (1); ischemic stroke (1); liposarcoma (1); liver fibrosis (1); lung (1); Myocardial fibrosis (1).
A further 12 diseases each share a sentence with PFN1 in 1 paper.